R3HDM2 (R3H domain containing 2)
Synonyms: KIAA1002; CAG6; PR01365
Tractability: PROTAC: ubiquitination databases record sites on it; its protein half-life has been measured.
Gene: Protein-coding gene on chromosome 12 (57,253,762 to 57,431,043, reverse strand). Ensembl gene ENSG00000179912.
Subcellular location: Nucleus
Subcellular location (Human Protein Atlas): Nucleoplasm
Gene Ontology:
Molecular function: protein binding; RNA binding; nucleic acid binding
Cellular component: nucleoplasm; nucleus
Genetic constraint (gnomAD): Loss-of-function variants: 30 observed, 104.51 expected, observed/expected ratio (o/e) 0.29, 90% interval 0.21 to 0.39. The upper end of that interval is the gene's LOEUF score, 0.39, which puts it in group 1 of 6, group 1 being the genes least tolerant of losing a copy. Missense variants: 833 observed, 1,188.8 expected, observed/expected ratio (o/e) 0.7, 90% interval 0.66 to 0.74. Synonymous variants: 379 observed, 426.43 expected, observed/expected ratio (o/e) 0.89, 90% interval 0.82 to 0.97.
Homologues: Orthologues: macaque R3HDM2 (99% identical), chimpanzee R3HDM2 (99% identical), pig R3HDM2 (97% identical), rabbit R3HDM2 (97% identical), mouse R3hdm2 (96% identical), guinea pig R3HDM2 (95% identical), rat R3hdm2 (95% identical), dog R3HDM2 (89% identical), tropical clawed frog r3hdm2 (75% identical), zebrafish r3hdm2 (62% identical). Paralogues in human: R3HDM1 (53% identical), ARPP21 (35% identical).
Diseases named in the same sentence as R3HDM2 in open-access papers:
R3HDM2 is named in the same sentence as 4 diseases in open-access papers, as found by Europe PMC text mining. Sharing a sentence is not in itself a finding about the gene and the disease. The quoted sentences say what the papers report.
Menière's disease (1 paper, 2021). "From our identified miRNAs, miRNA-1299 was identified as the most promising biomarker for Menière's disease since it is differentially regulated in both perilymph and serum of Menière's patients, and is predicted to target R3HDM2, SCP2, and ATP5PO mRNA." (PMID 34220670, 2021).
metastatic melanoma (1 paper, 2021). A melanoma that has spread from its primary site to another anatomic site. "CYT-high metastatic melanomas had recurrent copy number amplifications in loci 1p12 (NOTCH2), 1q44 (OR2M4), 7q36.1 (KCNH2), 11q13.3 (FGF3/4), 12p11.23 (MED21) and 12q13.3 (R3HDM2) and deletions in 1p22.1 (RHOC, NRAS), 9p21.3 (CDKN2B), 10q23.2 (miR346), 11q23.3 (ATM, CHEK1, ETS1) and 15q15.3 (CASC4)." (PMID 33779796, 2021).
Sepsis (1 paper, 2024). Sepsis is defined as life-threatening organ dysfunction caused by a dysregulated host response to infection. "R3HDM2, linked to uric acid transport, aligns with our investigation and strengthens the potential genetic connection between BUN and sepsis." (PMID 39086896, 2024).
R3HDM2 also shares sentences with these, for which no sentence is quoted: gout (1 paper).